ALK (ALK receptor tyrosine kinase)
Diseases named in the same sentence as ALK in open-access papers (continued):
Sharing a sentence is not in itself a finding about the gene and the disease.
lung cancer (continued). "Interestingly, these mutations are paralogous to resistance mutations that have been identified after progression on ALK tyrosine kinase inhibitor therapy in ALK fusion-positive lung cancers, and ROS1 tyrosine kinase inhibitor therapy in ROS1 fusion-positive lung cancers." (PMID 31738426, 2019). "Moreover, metformin was found to reverse resistance to TKIs and ALK inhibitors in lung cancer." (PMID 31795465, 2019). "Treatment strategies of lung cancers have expanded greatly in recent years with the development of targeting therapy in cancer-specific oncogenic driver mutations, such as the epidermal growth factor receptor (EGFR), the anaplastic lymphoma kinase (ALK) and ROS1 rearrangements." (PMID 29515799, 2018). "However systemic therapy for lung cancer has been revolutionized for the subsets of patients with an EGFR mutation, ALK rearrangement or PD-L1 positivity by targeted agents which are initiated in appropriate clinical scenarios and based on widely available predictive biomarkers." (PMID 30364202, 2018). "Moreover, high levels of MET amplification defined as MET:CEP7 > 5 were previously identified as actionable driver mutations predicting sensitivity of the tumor to the inhibitors of kinase MET, including crizotinib, currently approved for the treatment of ALK or ROS1-rearranged lung cancers." (PMID 28137276, 2017). "Therefore, the detection of ALK-rearrangement is fundamental for personalized lung cancer therapy." (PMID 28549458, 2017). "Thus, a drug designed to treat ALK mutations would qualify for orphan designation status if the number of patients with that mutation across all cancers, rather than just lung cancer, was less than the 200,000-patient threshold." (PMID 28045970, 2017). "Additionally, in some cases, false-positive results in diagnostics may contribute to observed resistance, as has been documented for ALK rearrangements in lung cancer." (PMID 28685150, 2017). "Thus, it is anticipated that an additional order of magnitude of genetic aberrations co-occurring with ALK fusions in lung cancer could be detected with whole genome or whole exome sequencing analysis." (PMID 29189709, 2017). "These previously unappreciated co-occurring genetic alterations as well as the activation of IGF-1R-IRS-1 pathway may cooperate with the oncogenic function of ALK in promoting lung cancer progression and therapy resistance in both the targeted therapy-naïve and the acquired resistance setting." (PMID 29189709, 2017). "The Ion AmpliSeq RNA Lung Cancer Research Fusion Panel is based on an amplicon target enrichment approach that allows amplification and detection of 70 known fusion transcripts for the ALK, RET, ROS1, and NTRK1 genes using a couple of primers specific of each fusion." (PMID 28970558, 2017). "Finally, we examine the potential of targeting ALK fusion-specific neoantigens in combination with other treatments, a strategy that could open a new avenue for the improved treatment of ALK positive lung cancer patients." (PMID 29189709, 2017). "Importantly, in both normal and lung cancer cells ESRP1/2 were regulated by ALK oncogenic activity." (PMID 27119231, 2016). "The present study also revealed that EGFR mutations in advanced lung carcinoma were more frequently associated with intra-thoracic metastases to the lung and pleura, and the absence of lymphadenopathy and extranodal invasion, compared to the KRAS and ALK mutations." (PMID 27518729, 2016). "Therefore, Hsp90 could be an alternative therapeutic target instead of direct kinase inhibition in ALK-driven lung cancer." (PMID 26219569, 2015). "However, emerging genomic data are revealing common ALK point mutations in various cancer types other than lung cancer, and several recent studies have demonstrated that ALK point mutations, independent of ALK gene rearrangements, can be oncogenic." (PMID 26373952, 2015). "In addition, we summarize future therapeutic strategies for ALK-positive lung cancer patients." (PMID 25941796, 2015).
lung cancer (continued). "Treatment of lung cancer has moved towards individualized treatment using the combined assessment of immunohistochemical markers, mutational analyses, and FISH techniques in order to assess the exact histology and to detect, for example, KRAS and EGFR mutations or ALK translocations." (PMID 25968475, 2015). "In 2013, the College of American Pathologists, International Association for the Study of Lung Cancer, and Association for molecular Pathology established guidelines for the molecular testing of all advanced stage lung adenocarcinomas for EGFR mutations and ALK rearrangements prior to treatment." (PMID 26603430, 2015). "In addition to the EML4-ALK fusion gene in lung cancer, various ALK-related diseases have been reported, including familial neuroblastoma, renal cell carcinomas, esophageal squamous cell carcinomas, breast cancer, colonic adenocarcinomas, glioblastoma multiforme, and anaplastic thyroid cancer." (PMID 25941796, 2015). "Lung cancer genetic mutation screening for known oncogenes—epidermal growth factor receptor (EGFR) mutation and anaplastic lymphoma kinase (ALK) rearrangements—were ordered to evaluate whether the tumor could be treated with tyrosine kinase inhibitors, such as erlotinib and crizotinib." (PMID 26425638, 2015). "Namely, the changes in IRS-1 might be specific to ALK-positive lung cancer." (PMID 25941796, 2015). "Last, advanced stage ALK-positive lung cancers may have a higher propensity for pleural and pericardial disease than lung cancers lacking ALK, KRAS, or EGFR mutations." (PMID 24955213, 2014). "Another study on circulating tumor cells (CTCs) in lung cancer suggested that homogeneous mesenchymal phenotype was observed in ALK-rearranged CTCs, which indicated EMT may be triggered by ALK tyrosine kinase activation and then promotion of tumor cell migratory properties." (PMID 25277203, 2014). "This combination could also be suitable for the screening of ALK-positive lung cancer." (PMID 25295103, 2014). "In the present study, as the distribution scores of ALK in each method were relatively high, IHC for ALK may have low heterogeneity, suggesting that using IHC for ALK could be useful in limited tissue samples, such as in biopsy specimens or cytology, for the screening of ALK-positive lung carcinoma." (PMID 25295103, 2014). "None of the ALK-positive lung carcinomas harbored coexisting EGFR mutations in the present study." (PMID 25295103, 2014). "However, the prevalence of ALK rearrangement in lung carcinomas varies significantly." (PMID 25077070, 2014). "Cell line experiments have also shown that both EGFR and MET activation and the interaction between the corresponding signaling pathways may mediate crizotinib resistance, suggesting that both signaling by EGFR and MET may be crucial for the survival of lung cancer cells upon ALK inhibition." (PMID 24279718, 2013). "Similarly, lung cancers frequently overexpress ALK and ROS1, which may be inhibited by GTx-186 or crizotinib." (PMID 24386191, 2013). "Therefore, it is unlikely that the left lung cancer is ALK fusion-positive." (PMID 23617234, 2013). "Therefore, molecular tests are routinely performed to identify mutations in oncogenes in lung cancer, including EGFR and ALK; to identify those patients with a high likelihood of response to targeted therapy; and reduce unnecessary side effects of ineffective treatments." (PMID 23198868, 2012). "Of the 3 histopathologically confirmed ALK fusion partners in lung cancer, EML4 colocalizes with microtubules and may contribute to the stabilization of microtubules, KIF5B moves on the microtubules as a kinesin heavy chain, and KLC1 binds to kinesin heavy chains as a kinesin light chain." (PMID 22347464, 2012). "Also, constitutively activated ALK is known to carry prognostic value in cancers such as lung cancer and ALCL, thus providing further evidence that mutations in LTK that induce constitutive signaling may provide clinically important information." (PMID 22347506, 2012).
lung cancer (continued). "In previous studies, the toxicity profiles of TKIs in lung cancer therapy have been extensively studied for EGFR and ALK inhibitors." (PMID 40949148, 2025). "Whilst a diagnosis of non‐small cell lung cancer (NSCLC) in pregnancy is rare, anaplastic lymphoma kinase (ALK)-rearranged NSCLCs accounts for 38% of NSCLC in women of childbearing age." (PMID 40385633, 2025). "Specifically, in the field of lung cancer, this catalog advocates the inclusion of PD-L1, EGFR, ALK, ROS-1, KRAS, NTKR, RET, and MET." (PMID 40261489, 2025). "This can be attributed to both the rapid advancement in China’s research capabilities and its large population of ALK-positive NSCLC patients, given the high prevalence of lung cancer in the country." (PMID 40894217, 2025). "For instance, it has been demonstrated that drug resistance and lung cancer metastasis are significantly influenced by the interaction between KLC1 and ALK." (PMID 40421300, 2025). "The discovery of therapeutically targetable gene fusions, such as ALK, RET, ROS1, and NTRK1, has significantly advanced lung cancer management." (PMID 39810398, 2025). "This study adopts a structure-guided and expression-validated approach to characterize EGFR, ALK, KRAS, and PD-1—four of the most clinically actionable targets in lung cancer." (PMID 40927719, 2025). "For the first time, the current study reported that rapamycin has a binding affinity with ALK, EGFR, FGFR, MET, and ROS1 receptors expressed in the lung cancer cells." (PMID 39762538, 2025). "In summary, targeted therapies in lung cancer exemplify the paradigm of drugging specific oncogenic drivers such as EGFR, ALK, and KRAS, thereby providing substantial clinical benefit for well-defined molecular subgroups." (PMID 41472727, 2025). "Among these, gene fusions involving the anaplastic lymphoma kinase (ALK) and ROS proto-oncogene 1 (ROS1), though rare, are highly significant in the context of lung cancer diagnosis and treatment." (PMID 40739404, 2025). "The correlation between TEs and oncogenic drivers in lung cancer is not well understood yet, necessitating further investigation, particularly concerning the elevated risks of TEs in patients with ROS1 and ALK rearrangements." (PMID 40751559, 2025). "In ALK-positive metastatic non–small-cell lung cancer (NSCLC) patients, alectinib, a second-generation ALK inhibitor, had a greater response rate than crizotinib with less toxicity." (PMID 40700600, 2025). "Discovery and drug development of new lung cancer‐related targets: EGFR, ALK, ROS1, RET, MET, BRAF inhibitors, etc." (PMID 40135802, 2025). "ALK gene fusions have been reported frequently in lung cancer, especially in non-small-cell lung cancer, and EML4-ALK is known to be the most frequent driver gene." (PMID 40647546, 2025). "Originally developed as an ALK and ROS1 inhibitor for the treatment of non‐small cell lung cancer (NSCLC), the newfound ability of crizotinib to inhibit CD147 and MCT1 extends its therapeutic potential into the realm of cancer metabolic reprogramming." (PMID 40692663, 2025). "Later, the rearrangements in the ALK gene, discovered in a subgroup of NSCLC and called ALK‐positive, were demonstrated to be responsible for the development of lung cancer." (PMID 41213866, 2025). "The STRING protein–protein interaction (PPI) analysis of EGFR, ALK, KRAS, and PD-1 revealed a complex, yet functionally coordinated molecular landscape in lung cancer." (PMID 40927719, 2025).
lung cancer (continued). "Approximately 80–85% of all lung cancer can be classified as non-small cell lung cancer (NSCLC), of which 3–7% were identified with anaplastic lymphoma kinase (ALK) gene rearranged (referred as ALK-positive)." (PMID 41313568, 2025). "Consequently, ICIs may enhance treatment outcomes in patients with ALK-resistant lung cancer." (PMID 40873540, 2025). "The aim of the current study is to investigate the prevalence of alterations in the eight most frequently altered genes in lung cancer—BRAF, EGFR, KRAS, ALK, ROS1, HER2, PD-L1 and PIK3CA." (PMID 41153394, 2025). "EGFR, ALK, VEGF, and KRAS are the most important signaling pathways which have been identified and are involved in the progression of lung cancer." (PMID 38234663, 2024). "The main targeted treatments approved for lung cancer with ROS1 rearrangement include drugs such as Crizotinib, a tyrosine kinase inhibitor initially approved for ALK-positive patients, which has shown significant efficacy in ROS1-positive patients as well." (PMID 39199653, 2024). "We looked at the distribution of breakpoints in ALK, RET, ROS1, NTRK1, as well as other kinase genes known to generate oncogenic fusions in lung cancer, such as EGFR, ERBB4, MET, FGFR3, and EPHA245." (PMID 38877018, 2024). "In total, 66 samples obtained from 30 patients with lung cancer pre-TKI or post-TKI therapy (erlotinib (EGFR), osimertinib (EGFR) and crizotinib (ALK) being the most frequent targeted therapies) were analyzed." (PMID 38049664, 2024). "In the study of lung cancer proteomics, proteins in receptor tyrosine kinases such as EGFR and ALK and their downstream signalling pathways play a key role in the pathological process of lung cancer." (PMID 39391313, 2024). "The median CYFRA21‐1:CEA ratio was 0.395 for the ALK‐positive lung cancer group, which was significantly higher compared with 0.098 for the EGFR‐positive lung cancer group." (PMID 38400801, 2024). "For instance, NTRK fusions (across all cancer types) but also other kinase fusions (for example, ALK, ROS and RET for lung cancers), are now included in the NGTDC." (PMID 38200255, 2024). "The patient in our case was receiving alectinib, a tyrosine kinase (ALK and RET kinases) receptor inhibitor, as targeted therapy for lung cancer, which, while effective, can contribute to immunosuppression and increase susceptibility to infections." (PMID 39330913, 2024). "As a second‐generation of ALK‐TKI, ensartinib hold superior efficacy to crizotinib and had been approved for the first‐line treatment in patients with ALK‐positive nonsmall cell lung cancer (NSCLC)." (PMID 39667359, 2024). "ALK‐ and EGFR‐positive lung cancers are predominantly adenocarcinomas, but there are differences in pathological subtypes." (PMID 38400801, 2024). "Anaplastic lymphoma kinase (ALK; also known as ALK tyrosine kinase receptor) inhibitors (ALKi) are effective in treating lung cancer patients with chromosomal rearrangement of ALK." (PMID 39540457, 2024). "Further research is warranted to explore and elucidate the underlying mechanisms responsible for the difference in CYFRA21‐1 values between ALK‐ and EGFR‐positive lung cancers." (PMID 38400801, 2024). "We selected 134 cases of advanced or recurrent ALK‐positive and 172 cases of advanced or recurrent EGFR‐positive lung cancer from our clinical database." (PMID 38400801, 2024). "This interaction amplifies lung cancer growth through the upregulation of oncogenic factors like MMP9 and anaplastic lymphoma kinase (ALK), and the downregulation of tumour suppressor genes such as kruppel‐like factor 6 (KLF6)." (PMID 39304978, 2024). "Comparison of clinical characteristics of patients with ALK‐ and EGFR‐positive lung cancer categorized according to the CYFRA21‐1:CEA ratio." (PMID 38400801, 2024). "In the context of lung cancer, EGFR, ALK, KRAS, BRAF, Bcl-xl, SHP2 and FAK, E3 ligase ligands, are potential oncogenic targets of PROTACS." (PMID 39456995, 2024).
lung cancer (continued). "A higher proportion of patients with ALK‐positive lung cancer were CYFRA21‐1 positive and had higher CYFRA21‐1:CEA ratios compared with EGFR‐positive lung cancer patients." (PMID 38400801, 2024). "In this study, significant differences in age and sex were also observed between patients with ALK‐positive and EGFR‐positive lung cancers, although the effects of age and sex on tumor markers are unclear." (PMID 38400801, 2024). "Recently, it has been shown that the ALK and ROS1 genes driving lung cancer are also present in colorectal cancer." (PMID 38770671, 2024). "Although alectinib remains the standard of care for ALK + NSCLC, some of the ALK+ lung cancer cells transiently become resistant to alectinib, and, over time, this leads to treatment resistance." (PMID 39551860, 2024). "The roles of lung cancer-related genes, such as KRAS, EGFR, and ALK, have been systematically investigated in specific animal models of cancers." (PMID 39311119, 2024). "Given that ROS1-rearranged lung cancers often feature solid growth with signet ring cells or cribriform morphology with abundant extracellular mucus, these tumors may also present with calcifications similar to those observed in EGFR-mutated and ALK-rearranged lung cancers." (PMID 39391406, 2024). "ALK and RET gene fusions are significant driver genes in lung adenocarcinoma, and targeted therapies have been approved for these alterations in lung cancer." (PMID 39583122, 2024). "In conclusion, our study showed that one twentieth of lung cancer patients diagnosed in Germany in 2016 received at least one EGFR, ALK, or BRAF inhibitor during follow‐up." (PMID 39693368, 2024). "In our study, 49 (12.5%) of the lung cancer patients treated with EGFR, ALK, or BRAF inhibitors were diagnosed at a non‐advanced stage." (PMID 39693368, 2024). "Among lung cancer cells, NCI-H3122 cells with EML4-ALK v1 tended to be more sensitive to ALK TKIs than NCI-H2228 cells with EML4-ALK v3a/b." (PMID 38829559, 2024). "One twentieth of lung cancer patients diagnosed in 2016 in Germany received at least one EGFR, ALK, or BRAF inhibitor during follow‐up." (PMID 39693368, 2024). "We investigated the impact of tumor marker values on performance status (PS) and distant metastasis in patients with ALK‐positive and EGFR‐positive lung cancer." (PMID 38400801, 2024). "The presence of ALK and PDL-1 biomarkers also provides opportunities for targeted therapies, which are increasingly becoming standard care in advanced lung cancer." (PMID 39597963, 2024). "Of 205 EGFR‐positive lung cancer patients, 172 cases of advanced or recurrent EGFR‐positive lung cancer were analyzed, excluding recurrence‐free cases and comutations with ALK." (PMID 38400801, 2024). "In lung cancer, MET and ALK are the most commonly encountered driver genes, but they have different carcinogenic mechanisms." (PMID 39751645, 2024). "Non-small cell lung cancer (NSCLC) accounts for approximately 85% of lung cancer, and 3–5% of NSCLC has a gene rearrangement of analplastic lymphoma kinase (ALK)." (PMID 38616252, 2024). "Non-small cell lung cancer (NSCLC) accounts for approximately 80–85% of lung cancer, and approximately 5% of NSCLC tumors harbor anaplastic lymphoma kinase (ALK) gene rearrangements." (PMID 38699428, 2024). "Our study provides, for the first time, insights into the real‐world utilization of EGFR, ALK, and BRAF inhibitors in the therapy of lung cancer patients in Germany." (PMID 39693368, 2024). "Although patients with ALK fusions showed response to ensatinib in nonsmall cell lung cancer (NSCLC), this study first reports a metastatic NET case with a novel CEP44‐ALK rearrangement that responded favorably to ensartinib." (PMID 39667359, 2024). "As a tyrosine kinase in the insulin receptor kinase subfamily, anaplastic lymphoma kinase (ALK) is a potent and promising oncogenic factor in lung cancer." (PMID 37261210, 2023).